PAQR3 (progestin and adipoQ receptor family member 3)
Description:
Golgi-scaffold protein which modulates its interactors acitivies by anchoring them to the Golgi apparatus. Functions as a spatial regulator of RAF1 kinase by sequestrating it to the Golgi apparatus. Acts as a positive regulator of cholesterol biosynthesis by mediating the anchoring of the SCAP:SREBP complex in the Golgi apparatus, thereby promoting SCAP:SREBF2 complex formation, potentiating SREBF2 and SREBF1 processing and enhancing lipid synthesis. Also regulates PPARA and PPARG functions by mediating their interaction with E3 ubiquitin ligases, such as STUB1 or HUWE1, leading to their polyubiquitination and proteasome-mediated degradation (By similarity).
Synonyms: RKTG
Tractability: Antibody: UniProt predicts a signal peptide or a membrane-spanning region. PROTAC: ubiquitination databases record sites on it.
Gene: Protein-coding gene on chromosome 4 (78,887,127 to 78,939,438, reverse strand). Ensembl gene ENSG00000163291.
Subcellular location: Golgi apparatus membrane
Pathways (Reactome):
Signal Transduction: Negative regulation of MAPK pathway
Gene Ontology:
Molecular function: protein binding; protein-membrane adaptor activity; ubiquitin-like ligase-substrate adaptor activity
Biological process: negative regulation of MAP kinase activity; negative regulation of neuron projection development; negative regulation of peptidyl-serine phosphorylation; negative regulation of protein phosphorylation; positive regulation of cholesterol biosynthetic process; positive regulation of SREBP signaling pathway; protein localization to Golgi apparatus; negative regulation of peroxisome proliferator activated receptor signaling pathway; positive regulation of proteasomal ubiquitin-dependent protein catabolic process
Cellular component: Golgi apparatus; Golgi membrane; membrane
Genetic constraint (gnomAD): Loss-of-function variants: 39 observed, 43.54 expected, observed/expected ratio (o/e) 0.9, 90% interval 0.69 to 1.17. The upper end of that interval is the gene's LOEUF score, 1.17, which puts it in group 5 of 6, group 1 being the genes least tolerant of losing a copy. Missense variants: 366 observed, 405.41 expected, observed/expected ratio (o/e) 0.9, 90% interval 0.83 to 0.98. Synonymous variants: 140 observed, 149.7 expected, observed/expected ratio (o/e) 0.94, 90% interval 0.81 to 1.08.
Homologues: Orthologues: macaque PAQR3 (99% identical), dog PAQR3 (99% identical), rabbit PAQR3 (99% identical), guinea pig PAQR3 (98% identical), mouse Paqr3 (98% identical), pig PAQR3 (97% identical), rat Paqr3 (97% identical), chimpanzee PAQR3 (87% identical), tropical clawed frog paqr3 (83% identical), zebrafish paqr3a (76% identical), zebrafish paqr3b (76% identical), Drosophila melanogaster CG7530 (36% identical), and 1 more. Paralogues in human: ADIPOR2 (31% identical), ADIPOR1 (31% identical), PAQR7 (21% identical), PAQR8 (20% identical), PAQR5 (19% identical), PAQR9 (19% identical), PAQR6 (19% identical), PAQR4 (18% identical), MMD2 (13% identical), MMD (11% identical).
Diseases named in the same sentence as PAQR3 in open-access papers:
PAQR3 is named in the same sentence as 53 diseases in open-access papers, as found by Europe PMC text mining. Sharing a sentence is not in itself a finding about the gene and the disease. The quoted sentences say what the papers report.
gastric cancer (7 papers, 2017 to 2025). A primary or metastatic malignant neoplasm involving the stomach. "In gastric cancer, research has shown that PAQR3 facilitates the interaction between Twist1 and the ubiquitination ligase BTRC, accelerating Twist1 degradation and ultimately inhibiting epithelial–mesenchymal transition (EMT) and metastasis." (PMID 40723340, 2025). "Based on the discovery that the N-terminal region (amino acids 6-55) of PAQR3 binds to P110α and suppresses the growth of gastric cancer, a synthetic peptide (P6-55) mimicking this region was designed." (PMID 40723340, 2025). "It is noteworthy that PAQR3 exhibits significantly low expression in gastric cancer tissues, and its expression is negatively correlated with tumor size, stage, metastasis, and patient survival rate." (PMID 40723340, 2025). "The CRL4DDB2 ubiquitin ligase can also promote the growth and migration of gastric cancer cells by mediating the proteosome degradation of PAQR3." (PMID 35813480, 2022). "PAQR3 was recently discovered as a new member of tumor suppressor that is deregulated in different types of human cancer including colon cancer, gastric cancer, bladder cancer, liver cancer, osteosarcoma, breast cancer, and laryngeal squamous cell carcinoma." (PMID 28903314, 2017). "Notably, the peptide synthesized from 6 to 55 amino acids at the N-terminal of PAQR3 (P6-55) has been shown to effectively inhibit the growth of gastric cancer cells." (PMID 40723340, 2025). "Given that P6-55 can substitute for PAQR3 to perform specific functions and effectively inhibit the growth of gastric cancer cells, we aimed to investigate whether P6-55 could similarly inhibit the proliferation and migration of colon cancer cells." (PMID 40723340, 2025). "Previous studies showed that PAQR3 is a newly discovered gene with a potential tumor suppressor function in a variety of tumors, with low expression in liver cancer, colorectal cancers, gastric cancer, etc., and significantly negatively correlated with patient tumor progression and poor prognosis." (PMID 35870178, 2022). "In addition, DDB2 interacts with PAQR3 to modulate the tumorigenesis of gastric cancer." (PMID 33955706, 2021). "This peptide retains the critical binding domain with P110α and effectively emulates PAQR3’s PI3K-inhibitory function, significantly suppressing the proliferation of gastric cancer cells and tumor formation." (PMID 40723340, 2025). "Lately, we found that PAQR3 is able to regulate ubiquitination and degradation of Twist1, a master regulator of EMT in gastric cancer cells." (PMID 28903314, 2017). "Our previous studies have found that PAQR3 plays a role as a candidate inhibitor in cardiac adenocarcinoma, breast cancer, gastric cancer and colorectal cancer, but the systematic analysis of PAQR3 in tumors is currently lacking." (PMID 38321173, 2024). "RKTG/PAQR3 suppresses EMT phenotype, migration and invasion of multiple cancer cells (including gastric cancer, prostate cancer and glioma cells) by inhibiting not only Ras/Raf/MEK/ERK signaling but also the PI3K/AKT pathway by trapping to the GC key players in these cascades." (PMID 35805075, 2022).
breast carcinoma (6 papers, 2015 to 2025). "In contrast, miR-15b has been implicated in promoting breast cancer progression by targeting and inhibiting the tumour suppressor gene PAQR3." (PMID 40407536, 2025). "Collectively, these data not only pinpoint that PAQR3 expression level is markedly altered in human breast cancers, but also suggest that such change is closely associated with HER2 expression in the tumors." (PMID 25900239, 2015). "We report here that PAQR3 is associated with the progression and survival of human patients with breast cancer, as well as cell proliferation and migration of human breast cancer cells." (PMID 25900239, 2015). "It is therefore imperative in the future to fully uncover the molecular mechanisms underlying that functional interaction between HER2 and PAQR3 in breast cancer development." (PMID 25900239, 2015). "Furthermore, the expression status of PAQR3 was associated with the survival of the breast cancer patients." (PMID 25900239, 2015). "In human breast cancer, the expression of PAQR3 is decreased and negatively correlated with that of HER2." (PMID 33123538, 2020). "The mRNA level of PAQR3 was determined in both the primary breast cancer samples together with their corresponding para-cancerous histological normal tissue (PCHNT)." (PMID 25900239, 2015). "At the clinical level, PAQR3 expression level was robustly downregulated in human breast cancer samples as compared to the adjacent normal tissues." (PMID 25900239, 2015). "In conclusion, PAQR3 expression is frequently downregulated in human breast cancers inversely correlated with HER2 expression." (PMID 25900239, 2015). "Consistently, the transwell assay also confirmed that the cell migration rate was significantly decreased by PAQR3 overexpression in these breast cancer cells." (PMID 25900239, 2015). "Our data indicate that PAQR3 functions as a tumor suppressor in the development of human breast cancers." (PMID 25900239, 2015). "The expression status of PAQR3 in the breast cancer samples was strongly correlated with the differentiation of the tumor (P < 0.0001), with low expression of PAQR3 associating with poor differentiation of the tumor." (PMID 25900239, 2015). "In this study, we have provided evidence that PAQR3 functions as a tumor suppressor in human breast cancers." (PMID 25900239, 2015). "At the cellular level, overexpression of PAQR3 negatively regulated cell proliferation, colony formation and migration of human breast cancer cells." (PMID 25900239, 2015). "To investigate the potential role of PAQR3 as a suppressor in human breast cancers, we characterized the expression status of PAQR3 transcript in 82 patients with primary breast cancer." (PMID 25900239, 2015). "PAQR3 mRNA level was robustly downregulated in human breast cancer samples compared with their corresponding para-cancerous histological normal tissues (n = 82, P < 0.0001)." (PMID 25900239, 2015). "PAQR3 overexpression inhibited cell proliferation, colony formation and migration of breast cancer cells including MCF7, SKBR3, MDA-MD-231, MDA-MD-468 and MDA-MD-453 cells." (PMID 25900239, 2015). "The silencing of gene expression by PAQR3 promoter hypermethylation may play an important role in breast cancer." (PMID 35178391, 2022). "PAQR3 inhibits the proliferation, clone formation, migration, and invasion of breast cancer cells." (PMID 33123538, 2020). "We next investigated whether PAQR3 has a direct effect on the growth and migration of breast cancer cells." (PMID 25900239, 2015). "Collectively, these data indicate that the expression level of PAQR3 might serve as an independent marker to predict the survival of the breast cancer patients." (PMID 25900239, 2015). "In this study, we investigated the potential functions of PAQR3 in human breast cancers." (PMID 25900239, 2015). "We also analyzed the potential role of PAQR3 on the migratory activity of breast cancer cells." (PMID 25900239, 2015).
breast carcinoma (continued). "PAQR3 is able to modulate the proliferation and migration of breast cancer cells." (PMID 25900239, 2015). "The wound healing assay revealed that overexpression of PAQR3 could significantly reduce the migration rate of all five breast cancer cell lines." (PMID 25900239, 2015). "However, the expression level of PAQR3 in Breast Cancer, Kidney Renal Clear Cell Carcinoma, Kidney renal papillary cell carcinoma, Prostate Adenocarcinoma, Rectum Adenocarcinoma, Thyroid Cancer and Uterine Corpus Endometrial Carcinoma was lower than that in normal tissues." (PMID 38321173, 2024). "Collectively, these data indicate that PAQR3 has a negative effect on the growth of breast cancer cells." (PMID 25900239, 2015). "PAQR3 is a newly discovered tumor suppressor and its functional role in breast cancer has not been well characterized." (PMID 25900239, 2015).
colorectal cancer (6 papers, 2014 to 2024). A primary or metastatic malignant neoplasm that affects the colon or rectum. "Interestingly, PAQR3 deletion is known to enhance tumorigenesis in mouse models, whereas the reduced expression in human colorectal cancer is associated with the regulation of the proliferation." (PMID 25372838, 2014). "This series of experiments demonstrated the tumor suppressor activity of PAQR3 in the development of colorectal cancer." (PMID 38115900, 2023). "For example, it has been mentioned in some studies that PAQR3 can inhibit MEK pathway activity in liver cancer, colorectal cancer and other tumors, and our analysis found that the expression level of PAQR3 is positively correlated with the effect of MEK inhibitors." (PMID 38321173, 2024). "Previous literature highlighted that PAQR3 could inhibit cell proliferation, migration, invasion, and EMT, by regulating the PI3K/AKT and Raf/MAPK/ERK signaling pathways in multiple cancers, including prostate, lung, and colorectal cancer." (PMID 34588429, 2021).
non-small cell lung carcinoma (4 papers, 2020 to 2025). A group of at least three distinct histological types of lung cancer, including non-small cell squamous cell carcinoma, adenocarcinoma, and large cell carcinoma. "For instance, PAQR3 expression has been found to be significantly downregulated in various malignancies, including laryngeal squamous cell carcinoma (LSCC) and non-small cell lung cancer (NSCLC)." (PMID 40391162, 2025). "In non-small cell lung cancer (NSCLC), PAQR3 suppresses tumor growth through multiple mechanisms." (PMID 40723340, 2025).
esophageal cancer (3 papers, 2020 to 2024). A primary or metastatic malignant neoplasm involving the esophagus. "In addition, the expression level of PAQR3 in Cholangiocarcinoma, Esophageal carcinoma, Head and neck squamous carcinoma, Liver Hepatocellular Carcinoma, Lung Adenocarcinoma and Lung squamous cell carcinoma was significantly higher than that in normal tissues." (PMID 38321173, 2024). "The level of PAQR3 was decreased both in tissues and cells of esophageal cancer, and overexpression of PAQR3 significantly inhibited the proliferation, clone formation, and invasion of esophageal cancer cells and blocked the transition from the G1 phase to the S phase." (PMID 33123538, 2020). "In addition, the expression of PAQR3 in esophageal cancer tissues is lower than that in normal esophageal tissues, and is significantly correlated with tumor size, lymph node metastasis, and local recurrence among esophageal cancer patients." (PMID 33123538, 2020). "Within the context of HNC, PAQR3 has been associated with tumorigenesis in oesophageal cancer, though to our knowledge no current literature has examined whether this gene affects oropharyngeal cancer specifically." (PMID 32600451, 2020).
lipid metabolism disorder (3 papers, 2017 to 2025). "It is thought that TMP can alleviate lipid metabolism disorders through downregulating PAQR3 and inhibiting SCAP/SREBP-1c signaling pathways." (PMID 35500001, 2022). "In conclusion, we showed that TMP could inhibit the progress of As and ameliorate lipid metabolism disorder by downregulating PAQR3 and inhibiting SCAP/SREBP-1c signaling pathway in ApoE−/− mice fed with a high-fat diet." (PMID 28491104, 2017). "In addition, TMP can inhibit the progress of As and ameliorate lipid metabolism disorder by downregulating PAQR3 and inhibiting SCAP/SREBP-1c signaling pathway in these mice." (PMID 28491104, 2017). "Thus, TMP may ameliorate lipid metabolism disorder and As by downregulating PAQR3 and inhibiting SCAP/SREBP-1c signaling pathway." (PMID 28491104, 2017).
lymph node metastasis (3 papers, 2020 to 2025). "In the Ualcan database, we found that the level of PAQR3 mRNA was significantly associated with race, smoking history, clinical stage, histological subtype, and lymph node metastasis among LUSC patients." (PMID 33123538, 2020). "In addition, Levels of PAQR3 were considerably reduced in NSCLC tissues and were associated with histological subtype, lymph node metastasis, and diagnosis of NSCLC in patients." (PMID 40391162, 2025). "In addition, the downregulation of PAQR3 is related to earlier pathological stage, lymph node metastasis, distant metastasis, larger tumor size, histological grade, and invasion depth in these patients." (PMID 40391162, 2025). "Furthermore, the level of PAQR3 mRNA was correlated with the histological subtype, lymph node metastasis, and tumor size, and was vital in the diagnosis of both NSCLC and its subtypes." (PMID 33123538, 2020). "The expression of PAQR3 was decreased in 60 NSCLC patients and was related to the histological subtype, lymph node metastasis, tumor size, and diagnosis of NSCLC." (PMID 33123538, 2020). "The expression level of PAQR3 in GCA tissues was significantly negatively correlated with Helicobacter pylori infection (p = 0.000), venous invasion (p = 0.000), invasion depth (p = 0.000), lymph node metastasis (p = 0.022), tumor stage (p = 0.000), and patient survival (p = 0.009)." (PMID 35870178, 2022).
acute lymphoblastic leukemia (2 papers, 2021 to 2023). Leukemia with an acute onset, characterized by the presence of lymphoblasts in the bone marrow and the peripheral blood. "PAQR3, a member of the Progestin and AdipoQ Receptor (PAQR) family, is a newly discovered tumor suppressor, and its expression is decreased in acute lymphoblastic leukemia (ALL)." (PMID 38072908, 2023).